TTC21B (tetratricopeptide repeat domain 21B)
Description:
Component of the IFT complex A (IFT-A), a complex required for retrograde ciliary transport and entry into cilia of G protein-coupled receptors (GPCRs). Essential for retrograde trafficking of IFT-1, IFT-B and GPCRs. Negatively modulates the SHH signal transduction (By similarity).
Synonyms: IFT139; Nbla10696; FLJ11457; JBTS11; NPHP12; IFT139B; THM1; FAP60; FLA17; CFAP60; ATD4; SRTD4
Tractability: PROTAC: ubiquitination databases record sites on it; its protein half-life has been measured.
Gene: Protein-coding gene on chromosome 2 (165,857,475 to 165,953,851, reverse strand). Ensembl gene ENSG00000123607.
Subcellular location: Cytoplasm, cytoskeleton, cilium axoneme
Subcellular location (Human Protein Atlas): Basal body; Centriolar satellite; Primary cilium; Connecting piece; Cytosol; End piece; Mid piece; Principal piece
Pathways (Reactome):
Organelle biogenesis and maintenance: Intraflagellar transport
Signal Transduction: Hedgehog 'off' state
Gene Ontology:
Molecular function: protein binding; chromatin binding
Biological process: protein localization to cilium; regulation of intraciliary retrograde transport; regulation of transcription by RNA polymerase II; cilium assembly; intraciliary retrograde transport; regulation of gene expression
Cellular component: intraciliary transport particle A; ciliary tip; cilium; axoneme
Genetic constraint (gnomAD): Loss-of-function variants: 106 observed, 149.98 expected, observed/expected ratio (o/e) 0.71, 90% interval 0.6 to 0.83. The upper end of that interval is the gene's LOEUF score, 0.83, which puts it in group 3 of 6, group 1 being the genes least tolerant of losing a copy. Missense variants: 1,387 observed, 1,449.7 expected, observed/expected ratio (o/e) 0.96, 90% interval 0.92 to 1. Synonymous variants: 468 observed, 500.38 expected, observed/expected ratio (o/e) 0.94, 90% interval 0.87 to 1.01.
Gene-disease validity (ClinGen):
ClinGen rates the evidence that TTC21B causes each of these diseases.
nephronophthisis 12 (autosomal recessive): Definitive.
Homologues: Orthologues: chimpanzee TTC21B (99% identical), macaque TTC21B (98% identical), dog TTC21B (90% identical), pig TTC21B (89% identical), guinea pig TTC21B (88% identical), rabbit TTC21B (86% identical), rat Ttc21b (86% identical), mouse Ttc21b (86% identical), tropical clawed frog ttc21b (77% identical), zebrafish ttc21b (68% identical), Caenorhabditis elegans ift-139 (30% identical). Paralogues in human: TTC21A (51% identical).
Diseases named in the same sentence as TTC21B in open-access papers:
TTC21B is named in the same sentence as 58 diseases in open-access papers, as found by Europe PMC text mining. Sharing a sentence is not in itself a finding about the gene and the disease. The quoted sentences say what the papers report.
ciliopathies (25 papers, 2016 to 2026). "A previous study analyzed similar modifier effects for Gpr63 in mice, where Ttc21b was ablated in homozygous form; Ttc21b is already known to control brain size, and mutations in this gene cause ciliopathies, including microcephaly." (PMID 36831309, 2023). "The TTC21B gene, which encodes the retrograde intraflagellar transport protein IFT139, is found mostly in association with ciliopathies in humans." (PMID 34805047, 2021). "Here, we report the case of a ciliopathy induced by a homozygous pathogenic variant in the TTC21B gene." (PMID 34957165, 2021). "Mice homozygous for a null allele of Ttc21b also have a spectrum of ciliopathy phenotypes, including microcephaly (small brain)." (PMID 31730647, 2019). "We prioritized TTC28 because variants in TTC7A (OMIM: 609332), a member of the same gene family, causes autosomal recessive gastrointestinal defects, and variants in TTC21B (OMIM: 612014) are reported in human ciliopathies." (PMID 30679815, 2019). "THM1 (also termed TTC21B or IFT139) encodes a component of the intraflagellar transport-A complex and mutations in THM1 have been identified in 5% of individuals with ciliopathies." (PMID 27482817, 2016). "Pathogenic variants of TTC21B account for approximately 5% of ciliopathy case." (PMID 41399018, 2025). "Similarly, resequencing of TTC21B gene in a large group of clinically diverse ciliopathies showed that variants in this gene account as severity modifiers in ~5% of ciliopathy patients." (PMID 39516462, 2024). "We proffer new insight in the complexity and phenotypic diversity of ciliopathies reporting biallelic variants in TTC21B in an individual meeting diagnostic criteria for BBS and experiencing both kidney and liver failure requiring combined organ transplantation." (PMID 35112343, 2022). "Similarly, resequencing of the TTC21B gene in a large group of clinically diverse ciliopathies showed that variants in this gene account as severity modifiers in ~5% of ciliopathy patients." (PMID 34188062, 2021). "Also, TTC21B mutations cause ciliopathies, and ciliary dysfunction leads to neuronal excitability, spontaneous myoclonus and susceptibility to pentylenetetrazol-induced seizures in mice." (PMID 28334860, 2017). "IFT-139(L810P) is the corresponding mutation to TTC21B(L795P) that causes ciliopathy." (PMID 27515926, 2016). "Knockdown of the ttc21b gene resulted in typical manifestations of ciliopathy at 3 days post-fertilization (dpf), including a curved body axis, hydrocephalus, pericardial edema, pronephric cysts, and abnormal otoliths in otic vesicles." (PMID 41216503, 2026). "Only two gRNAs against each of the two syndromic ciliopathy genes: Ttc21b47 and Cep29048 showed significant depletion in the Cas9+/− mice, and of these, only one gRNAs against Ttc21b exhibited more than 30% depletion." (PMID 41282224, 2025). "TTC21B in trans with other ciliopathy genes is postulated to contribute to the severity/penetrance of the primary ciliopathy." (PMID 35112343, 2022). "TTC21B in humans is a known ciliopathy gene and contributes to the pathophysiology of a number of ciliopathies." (PMID 31730647, 2019). "Notably, 84.4% of ttc21b morphants exhibited severe ciliopathy phenotypes, which was decreased to 18.4% by co-injection with WT TTC21B mRNA." (PMID 41216503, 2026). "Here, using mouse fibroblast cells, we investigated the function of IFT139 (Thm1, TTC21B) in Hedgehog signaling, cilia structure, and ciliary protein localization, as well as the effect of the P209L ciliopathy mutation on cell proliferation and Hedgehog signaling." (PMID 41099179, 2025). "TTC21B is recognized not only as the causal gene for Nephronophthisis (NPHP) and Jeune asphyxiating thoracic dystrophy (JATD) but also as a potential modifying factor across the spectrum of ciliopathies." (PMID 38671463, 2024).
ciliopathies (continued). "This is also true of other ciliopathies, for example, where mutations in TTC21B (which encodes IFT139) can cause both isolated nephronophthisis and syndromic Jeune asphyxiating thoracic dystrophy as well as showing extensive genetic interactions with other ciliopathy loci." (PMID 36268591, 2023). "The study found that SPAG6, TRAF3IP1, IFT22, and KIF3B showed lower correlations with ciliopathies, while IFT172, TTC21B, CEP290, ACTB, and DYNC1H1 were highly correlated." (PMID 40432967, 2025). "The Renal proteinuria gene list corresponded to some genetic kidney diseases (CAKUT, tubulopathies, ciliopathies) that result in secondary FSGS such as Dent disease (CLCN5, OCRL), nephronophthisis (TTC21B, NPHP4), ADTKD-UMOD and Imerslund-Grasbeck syndrome 1 (CUBN)." (PMID 37578539, 2024). "We report TTC21B, a new candidate BBS gene previously identified in other ciliopathies." (PMID 35112343, 2022).
nephronophthisis (13 papers, 2016 to 2024). Progressive tubulointerstitial injury, inherited in an autosomal recessive pattern, caused by mutations in genes involved in ciliary function, which may result in an end stage renal failure. "These include Dent disease (CLCN5, OCRL), AD tubulointerstitial kidney disease (ADTKD due to UMOD variants), nephronophthisis (TTC21B, NPHP4), Imerslund-Grasbeck syndrome 1 (CUBN) and papillorenal syndrome (PAX2)." (PMID 37578539, 2024). "Homozygous variants in tetratricopeptide repeat domain 21b (TTC21B) are associated with an array of different clinical entities including nephronophthisis, nephrotic range proteinuria, focal segmental glomerulosclerosis (FSGS), or global sclerosis." (PMID 37628633, 2023). "In C. elegans, loss of IFT 139 leads to formation of abnormal, short cilia, and mutations in the human gene encoding IFT139 (TTC21B) have been linked to nephronophthisis and thoracic dystrophy." (PMID 28513435, 2017). "In addition to nephronophthisis and laterality defects, our findings demonstrated that TTC21B should also be considered a candidate gene for biliary ciliopathy, such as TTC26, which further expands the phenotypic spectrum of TTC21B deficiency in humans." (PMID 36273201, 2022). "Biallelic variants in TTC21B have not be previously identified in BBS but are causative for both nephronophthisis (NPHP) and Juene Asphyxiating Thoracic Dystrophy." (PMID 35112343, 2022). "In addition, pathogenic variants in TTC21B have been reported in patients with SRTD with end-stage renal disease, as well as in isolated nephronophthisis." (PMID 33875766, 2021). "Nephronophthisis (1 NPHP1, 1 NPHP4, and 1 TTC21B found in our study) may also be a differential diagnosis of ADTKD in young adults; however usually, autosomal recessive inheritance distinguishes it from ADTKD." (PMID 38707821, 2024). "Mutations in TTC21B gene lead to a wide spectrum of phenotypes such as syndromic Jeune asphyxiating thoracic dystrophy (JATD) and nephronophthisis (NPHP) with or without extrarenal manifestations." (PMID 34957165, 2021).
epilepsy (6 papers, 2017 to 2024). A brain disorder characterized by episodes of abnormally increased neuronal discharge resulting in transient episodes of sensory or motor neurological dysfunction, or psychic dysfunction. "A TWAS has suggested three significant risk genes for epilepsy: tetratricopeptide repeat domain 21 B (TTC21B), RP11-375N15.2, and tankyrase (TNKS)." (PMID 37246165, 2023). "Biological prioritization implicates SCN1A, SCN2A, SCN3A, and TTC21B as the most likely genes underlying the signal at 2q24.3 for all epilepsy, focal epilepsy and genetic generalized epilepsy." (PMID 30531953, 2018). "Of note, we identified three risk genes (TTC21B, RP11-375N15.2, and TNKS) whose expression perturbation may have a role in epilepsy." (PMID 34456681, 2021). "More work is needed to elucidate the role of TTC21B in epilepsy." (PMID 34456681, 2021). "In addition, we also identified three genes (TTC21B, RP11-375N15.2, and TNKS) whose cis-regulated expression level are associated with epilepsy, indicating that risk variants may confer epilepsy risk through regulating the expression of these genes." (PMID 34456681, 2021). "Our study not only provides new insights into genetic architecture of epilepsy but also prioritizes potential molecular targets (including GRM3 and TTC21B) for development of new drugs and therapeutics for epilepsy." (PMID 34456681, 2021).
cystic kidney disease (5 papers, 2016 to 2023). A congenital or acquired kidney disorder characterized by the presence of renal cysts. "Although TTC21B has been intensively illustrated in numerous individuals with kidney diseases, including nephronophthisis type 12 and glomerular and cystic kidney diseases, our results found that TTC21B mutations were also associated with biliary ciliopathy, such as TTC26 mutations." (PMID 36273201, 2022).
Jeune syndrome (5 papers, 2013 to 2023). Jeune syndrome, also called asphyxiating thoracic dystrophy, is a short-rib dysplasia characterized by a narrow thorax, short limbs and radiological skeletal abnormalities including "trident" aspect of the acetabula and metaphyseal changes. "Further, mutations in additional IFT components including TTC21B/IFT139, DYNC2H1 and WDR19/IFT144 have been reported in association with Jeune syndrome." (PMID 24009529, 2013). "Yet, “mild” phenotypes seem to go beyond Sensenbrenner and Jeune syndromes, given the fact that mutations in the IFT genes TTC21B and WDR19 are also associated with isolated nephronophthisis." (PMID 22829176, 2013).
Hypertension (4 papers, 2016 to 2025). The presence of chronic increased pressure in the systemic arterial system. "Patients with TTC21B mutations frequently present with extrarenal manifestations, including myopia, situs inversus, cerebral aneurysm, hypertension and so on." (PMID 41399018, 2025). "Consistent with previous reports, three patients (75%) with TTC21B mutations in this cohort demonstrated moderate-to-heavy proteinuria accompanied with hypertension and edema." (PMID 41399018, 2025). "TTC21B is expressed in the primary cilium and some variants are associated with arterial hypertension." (PMID 36979743, 2023). "Careful literature review supports the notion that biallelic, often hypomorph, missense variants in TTC21B are commonly associated with early‐onset hypertension and histological features of both FSGS and NPHP." (PMID 35289079, 2022). "In conclusion, NPHP remains a diagnosis in patients presenting with moderate-to-heavy proteinuria, particularly when accompanied by characteristic features including positive family history, hypertension, and edema, with TTC21B emerging as the predominant pathogenic gene in this clinical subgroup." (PMID 41399018, 2025). "In addition, we review the genetic diagnoses associated with early‐onset hypertension in the Genomics England 100,000 Genomes Project and potential additional cases solved for TTC21B in this cohort." (PMID 35289079, 2022).
microcephaly (4 papers, 2017 to 2023). A congenital or acquired developmental disorder in which the circumference of the head is smaller than normal for the person's age and sex. "In order to further explore the role of Ttc21b in anterior embryonic development and potentially determine the mechanism leading to the microcephaly in Ttc21baln/aln mutants, we used the Wnt1-Cre and Ap2-Cre alleles to ablate Ttc21b in NCC’s and both NCC’s and surface ectoderm, respectively." (PMID 28291836, 2017). "We conclude from these data that ablation of Ttc21b in the forebrain is, surprisingly, insufficient to recapitulate the microcephaly we observed in the Ttc21baln/aln null embryos." (PMID 28291836, 2017). "Conversely, a mutation in Ttc21b causes genetic background-dependent microcephaly in mouse; quantitative trait locus analysis revealed a missense mutation in one genetic background but not the other that was able to enhance the Ttc21b neural phenotypes." (PMID 33178111, 2020). "The mosaicism of the EIIa-Cre germline ablation provided further evidence that loss of Ttc21b in the brain is not responsible for the microcephaly phenotype." (PMID 28291836, 2017). "Previous studies have demonstrated that mice lacking Ttc21b have impaired retrograde trafficking within the cilium and multiple organogenesis phenotypes, including microcephaly." (PMID 31730647, 2019). "Our study demonstrated that neither ablation of Ttc21b from the forebrain at E9.5 or E10.5 phenocopied the microcephaly observed in Ttc21baln/aln homozygous mutants." (PMID 28291836, 2017).
Renal insufficiency (4 papers, 2018 to 2025). A reduction in the level of performance of the kidneys in areas of function comprising the concentration of urine, removal of wastes, the maintenance of electrolyte balance, homeostasis of blood pressure, and calcium metabolism. "Both children exhibited identical renal failure symptoms, and the proband, mother, and father all tested positive for TTC21B gene mutations, suggesting an autosomal recessive inheritance pattern." (PMID 41378128, 2025). "We detected homozygous mutations in the ciliary gene TTC21B in four patients from one family with a renal ciliopathy phenotype comprising renal insufficiency and retinitis pigmentosa (Supplementary Results 1)." (PMID 29974258, 2018).
Dent disease (3 papers, 2021 to 2024). Dent disease is a rare genetic renal tubular disease characterized by manifestations of proximal tubule dysfunction. "UMOD, CLCN5, OCRL, NPHP4, and TTC21B may cause tubulointerstitial diseases such as ADTKD, NPHP, or Dent disease, but they are now included in the genetic panels for genetic screening of patients affected by FSGS, as they can phenocopy it." (PMID 37728640, 2024).
focal segmental glomerulosclerosis (3 papers, 2015 to 2023). A renal disorder characterized by sclerotic lesions in the glomeruli. "We report a 9-year-old male with focal segmental glomerulosclerosis requiring kidney transplant, primary ciliary dyskinesia, and biliary dysgenesis, found by research-based exome sequencing to have biallelic pathogenic TTC21B variants." (PMID 33547761, 2021). "Interestingly, a homozygous human mutation in another ciliary gene TTC21B has lately been implicated in a familial form of focal-segmental glomerulosclerosis, clinically characterized by nephrotic-range proteinuria and severe podocyte damage." (PMID 26331477, 2015).
Joubert syndrome (3 papers, 2017 to 2026). Joubert syndrome (JS) is characterized by congenital malformation of the brainstem and agenesis or hypoplasia of the cerebellar vermis leading to an abnormal respiratory pattern, nystagmus, hypotonia, ataxia, and delay in achieving motor milestones. "In humans, TTC21B is one of the most commonly mutated genes in ciliopathy patients, and variants are present in disorders of the cerebellum such as Joubert Syndrome." (PMID 29615573, 2017). "Interestingly, TTC21B variants are associated with Joubert syndrome patients." (PMID 29615573, 2017).
Obesity (3 papers, 2016 to 2025). Accumulation of substantial excess body fat. "While obesity and diabetes are not typical features of TTC21B mutation, a murine model showed that TTC21B/IFT139 knockout mice developed hyperphagic behavior and obesity, resulting in type II diabetes mellitus and fatty liver disease." (PMID 34957165, 2021).
situs inversus (3 papers, 2021 to 2025). A congenital condition in which there is complete right-to-left reversal of the position of the major thoracic and abdominal organs (that is, they are arranged in a mirror image of the normal positioning). "Previous studies and ours identified TTC21B mutations in several patients with situs inversus." (PMID 36273201, 2022).
cyst (2 papers, 2016 to 2021). A sac-like closed membranous structure that may be empty or contain fluid or amorphous material. "In contrast, inhibition of Hh signaling using GLI and SMO small molecule antagonists Gant61 and Sant2 respectively prevented cyst formation in kidney explants from Ttc21b/Ift139-conditional knockout, jck/Nek8/Nphp9 and Pkd1 mutant mice." (PMID 34055783, 2021).
Fabry disease (2 papers, 2021 to 2024). Fabry disease (FD) is a progressive, inherited, multisystemic lysosomal storage disease characterized by specific neurological, cutaneous, renal, cardiovascular, cochleo-vestibular and cerebrovascular manifestations. "Genetic findings that modified the diagnosis in 19 patients included mutations in patients with NPHP (NPHP1 [n = 4], TTC21B [n = 3], ANKS6 [n = 1], NPHP3 [n = 1], NPHP4 [n = 1]), collagenopathies (COL4A5 [n = 7], COL4A3 [n = 1]), and Fabry disease (GLA [n = 1])." (PMID 39363361, 2024).
myopia (2 papers, 2019 to 2025). "For example, mutations in TTC21B gene, which we found to be involved in the regulation of susceptibility to myopia, were shown to cause a syndromic form of retinal dystrophy." (PMID 31362747, 2019).
polycystic kidneys (2 papers, 2017 to 2023). "In a postnatal deletion of Ttc21b, increased GLI2 activity led to polycystic kidneys." (PMID 29615573, 2017).